TRIM16 (tripartite motif containing 16)
Diseases named in the same sentence as TRIM16 in open-access papers (continued):
Sharing a sentence is not in itself a finding about the gene and the disease.
ovarian carcinoma (2 papers, 2021 to 2024). A malignant neoplasm originating from the surface ovarian epithelium. "For example, TRIM16 has been associated with EMT in prostate, breast and ovarian cancer, and an association with Snail regulation has been shown for the first two cancer types." (PMID 34208621, 2021).
periodontitis (2 papers, 2020 to 2025). An acute or chronic inflammatory process that affects the tissues that surround and support the teeth. "Accordingly, TRIM16 overexpression alleviated periodontitis by promoting osteogenic differentiation of PDLSCs and inhibiting oxidative damage." (PMID 39626954, 2025). "Clinical data revealed reduced TRIM16 protein levels in the gingival tissues of patients with periodontitis compared to healthy controls." (PMID 39626954, 2025). "What’s more, significant downregulation of TRIM16 was observed in periodontal tissue of patients with periodontitis compared with tissues in healthy individuals." (PMID 33490087, 2020). "TRIM16 is also known as an oxidative stress-responsive protein that confers cytoprotective effects by reinforcing the intracellular antioxidant capacity during cerebral ischemia/reperfusion injury and periodontitis." (PMID 33490087, 2020). "Therefore, activation of TRIM16 may represent a promising strategy for the prevention and treatment of periodontitis." (PMID 39626954, 2025).
skin cancer (2 papers, 2012 to 2019). "TRIM16 is known to be secreted by keratinocytes; however, the effect of the loss of keratinocyte TRIM16 on skin cancer development is currently unknown." (PMID 31342168, 2019). "In contrast, TRIM16 nuclear translocation was markedly reduced in retinoid-resistant SCC cells, which further suggests that loss of TRIM16 nuclear expression may contribute to retinoid resistance in skin cancer cells." (PMID 22009481, 2012). "To study the role of TRIM16 in skin cancer development, we used the classical two-stage skin carcinogenesis challenge method outlined by Abel and colleagues for the C57/BL6 mouse strain." (PMID 31342168, 2019). "Further study is also needed to determine the relationship between expression of TRIM16 and clinical prognosis in skin cancer." (PMID 22009481, 2012). "To determine whether TRIM16 plays a role in skin cancer cell growth, we transiently transfected human TRIM16 plasmid DNA into three different SCC cell lines." (PMID 22009481, 2012). "We hypothesized that the effects of TRIM16 on cell growth may be mediated by effects on these cell cycle regulatory proteins in retinoid-resistant skin cancer cells." (PMID 22009481, 2012). "Thus, TRIM16 could play an important role in the induction of the differentiation pathway and be involved in skin cancer progression." (PMID 22009481, 2012). "Our findings also highlight activation of TRIM16 nuclear translocation or degradation of vimentin and E2F1 as potential novel therapeutic strategies for the treatment of skin cancers." (PMID 22009481, 2012).
skin squamous cell carcinoma (2 papers, 2012 to 2014). A carcinoma arising from the squamous cells of the epidermis. "We sought to determine the role of TRIM16 in skin squamous cell carcinoma (SCC) pathogenesis." (PMID 22009481, 2012).
steatosis (2 papers, 2023 to 2024). Increased lipid within the cytoplasm of cells. "Likewise, a more recent study has shown that TRIM16 attenuates hepatocyte steatosis and inflammation in a mouse NASH model by directly interacting with the phosphorylated form of TAK1 and promoting its degradation, leading to suppressed NASH development." (PMID 38206764, 2024).
actinic keratosis (1 paper, 2012). A precancerous lesion of the skin composed of atypical keratinocytes. "We have shown that TRIM16 expression was markedly reduced during the histological progression from normal skin to actinic keratosis and SCC." (PMID 22009481, 2012).
age (1 paper, 2024). A temporal measurement of the time period elapsed since an identifiable point in the life cycle of an organism. "This novel insight suggests that TRIM16 could be a potentially valuable target for preventing and treating age‐related sarcopenia." (PMID 39192479, 2024).
colorectal cancer (1 paper, 2025). A primary or metastatic malignant neoplasm that affects the colon or rectum. "It is reported that tripartite motif containing 16 (TRIM16) and 21 (TRIM21) degrade Snail to prevent EMT and block metastasis progression of colorectal cancer." (PMID 41385185, 2025).
disc degeneration (1 paper, 2021). "ROS is an important pathogenic pathway in disc degeneration 25, 26 and an inducer of LC3B and TRIM16 expression required for secretory autophagy 27-30." (PMID 33391467, 2021). "As oxidative stress is a major mediator of disc degeneration, we exposed (M0 differentiated) THP-1 cells to TBHP (an exogenous ROS donor) and examined TRIM16 and LC3B expression." (PMID 33391467, 2021). "As TRIM16 and LC3B are important biomarkers for secretory autophagy, this high level of co-localization strongly suggested that upregulated secretory autophagy contributed to the pathogenesis of disc degeneration." (PMID 33391467, 2021). "In our study, induction of IL-1β through secretory autophagy and more co-localization of secretory autophagy markers (TRIM16 and LC3B) in degenerated discs pointed that secretory autophagy may contribute to disc degeneration with IL-1β secretion." (PMID 33391467, 2021). "Activation of secretory autophagy in degenerated discs and induction of IL-1β release under oxidative stress suggested that ROS and TRIM16/LC3B reducer, such as MR409, may be effective against disc degeneration." (PMID 33391467, 2021).
fibrosis (1 paper, 2013). the formation of excess fibrous connective tissue in an organ or tissue in a reparative or reactive process. "From the gene expression and SNP analysis, and based on data demonstrating the encoded protein to affect the secretion of cytokines of relevance of fibrosis, Trim16 was further investigated as a fibrosis susceptibility gene." (PMID 23341783, 2013).
glioblastoma (1 paper, 2025). The most malignant astrocytic tumor (WHO grade IV). "Sanggenol L, a flavonoid from mulberry, enhances glioblastoma sensitivity to temozolomide by inhibiting mitophagy and inducing apoptosis through TRIM16‐mediated OPTN degradation." (PMID 40990506, 2025). "Moreover, the first evidence that SL upregulates TRIM16 expression is presented, which acts as an E3 ubiquitin ligase for OPTN degradation in glioblastoma." (PMID 40990506, 2025). "All methods consistently confirmed the interaction between TRIM16 and OPTN in glioblastoma cells." (PMID 40990506, 2025).
glioma (1 paper, 2025). A benign or malignant brain and spinal cord tumor that arises from glial cells (astrocytes, oligodendrocytes, ependymal cells). "This study is the first to identify TRIM16 as an upstream regulator of OPTN in glioma and to demonstrate that targeting this pathway can reverse TMZ resistance." (PMID 40990506, 2025). "Mechanistic studies revealed that SL targets the TRIM16–OPTN axis, a novel regulatory pathway in glioma biology." (PMID 40990506, 2025).
papilloma (1 paper, 2019). A benign epithelial neoplasm that projects above the surrounding epithelial surface and consists of villous or arborescent outgrowths of fibrovascular stroma. "However, loss of both copies of TRIM16 results in fewer papilloma." (PMID 31342168, 2019). "In the skin-specific TRIM16 heterozygous knockout mice, it is observed that a reduced latency and increased number of papilloma develop in TRIM16 heterozygous mice." (PMID 31342168, 2019). "We found an increased incidence of papilloma in the heterozygous TRIM16+/flox mice compared to wild-type and homozygous mice." (PMID 31342168, 2019). "Like TRIM16 knockout mice, Fwe mice have no dicernable phenotype but display a significantly lower number of papilloma after DMBA/TPA carcinogen treatment compared to wild-type and heterozygous mice." (PMID 31342168, 2019).
proteinopathies (1 paper, 2018). "Taken together, this work highlights the significance of TRIM16 in proteostasis and hints that therapeutic modulation of TRIM16 could be a potential strategy to treat proteinopathies including cancer." (PMID 30143514, 2018).
pulmonary fibrosis (1 paper, 2013). Chronic progressive interstitial lung disorder characterized by the replacement of the lung tissue by connective tissue, leading to progressive dyspnea, respiratory failure, or right heart failure. "In summary we demonstrate that genetic variation in Trim16 leads to its strain-dependent expression, which alters susceptibility to bleomycin-induced pulmonary fibrosis in mice." (PMID 23341783, 2013). "Further to elevated pulmonary fibrosis the increased Trim16 expression produced higher levels of both Il12/23-p40 and neutrophils in the bronchoalveolar lavage of congenic mice." (PMID 23341783, 2013). "This study shows that genetic variation in Trim16 affects both the lung tissue inflammatory response and the development of pulmonary fibrosis in mice and thus provides a novel pathway to fibrosis development for subsequent clinical investigation." (PMID 23341783, 2013). "Our functional studies showed that Trim16 injected into the specifically bred, and bleomcyin-treated, mice significantly increased their pulmonary fibrosis levels." (PMID 23341783, 2013). "In this work we moved from the mapped locus to the gene by demonstrating that overexpression of Trim16 can contribute to pulmonary fibrosis development in mice." (PMID 23341783, 2013). "With this system the elevated Trim16 expression significantly increased the pulmonary fibrosis of recipient congenic mice." (PMID 23341783, 2013).
renal carcinoma (1 paper, 2020). A carcinoma arising from the epithelium of the renal parenchyma or the renal pelvis. "Seven genes (TRIM8, TRIM11, TRIM16, TRIM24, TRIM27, TRIM32, and PML) were expressed in different renal cancer cell lines through the KM expression website." (PMID 33173411, 2020).
sarcopenia (1 paper, 2024). Progressive decline in muscle mass due to aging which results in decreased functional capacity of muscles. "Furthermore, we observed suppressed antioxidant activity and reduced TRIM16 expression in the skeletal muscle of aged mice, increasing the risk of sarcopenia development and progression." (PMID 39192479, 2024). "To explore whether TRIM16 overexpression could protect against age‐related sarcopenia, we administered intramuscular injections of AAV encoding TRIM16 to mice from the 18‐month‐D‐gal and 24‐month‐old groups." (PMID 39192479, 2024). "To further explore the regulatory role of TRIM16 in age‐related sarcopenia, we initially established aging mouse models and compared muscle mass and function between aged and young mice." (PMID 39192479, 2024). "Through in situ overexpression of TRIM16 in the skeletal muscle of aged mice, we observed its protective role in age‐related sarcopenia." (PMID 39192479, 2024). "However, the role of TRIM16 in facilitating SIRT‐1 against sarcopenia requires further investigation." (PMID 39192479, 2024). "TRIM16 emerges as a potential therapeutic target for age‐related sarcopenia." (PMID 39192479, 2024). "Notably, our study is the first to investigate TRIM16's regulatory role in sarcopenia, expanding our understanding of TRIM16 in this context." (PMID 39192479, 2024).
thyroid tumor (1 paper, 2021). A benign or malignant neoplasm affecting the thyroid gland. "Nuclear factors Brn-3α and TRIM16 modulating expression of steroid hormones play an essential role in developing thyroid tumors." (PMID 34319022, 2021). "The study aimed to study the AKT / mTOR signaling pathway components, transcriptional and growth factors, as well as steroid hormone receptors and nuclear factors Brn-3α and TRIM16 expression in the tissue of the primary thyroid tumor and metastases, depending on the BRAF- V600E status." (PMID 34319022, 2021).
cancer (32 papers, 2012 to 2026). A tumor composed of atypical neoplastic, often pleomorphic cells that invade other tissues. "There were significantly more mutations in SRRY domain of TRIM16, in which R456C and A542T were mutated in more than one cancer patient (F E = 2.94, p adjust = 1.68E−6)." (PMID 36461099, 2022). "In CNV, we observed that TRIM24 had more gain mutations and TRIM16 has more loss mutations in pan-cancer." (PMID 33173411, 2020). "Previous studies demonstrated that TRIM16 is involved in regulating the NF-κB signaling pathway, which plays a crucial role in cancer development and progression." (PMID 40608798, 2025). "According to our results, the expression of TRIM3 and TRIM16 genes in the cancer group undergoes a significant reduction to 0.45 and 0.29 fold, respectively." (PMID 36180926, 2022). "TRIM16 has been proven to be an important tumor suppressor, which affects the proliferation, autophagy of cancer cells." (PMID 35230201, 2022). "Firstly, the expression of the TRIM16 gene in the cancer group was compared with that of the normal group." (PMID 36180926, 2022). "Another study found that TRIM16, TRIM32, TRIM24, TRIM8, TRIM27, TRIM11, and PML are associated with cancer stem cells and the clinical prognosis of RCC, and affect tumor progression." (PMID 36261847, 2022). "Although most of the previous studies have indicated down regulation of TRIM16 in other cancers, they found a positive correlation between TRIM16 expression and GC progress." (PMID 34452557, 2021). "TRIM16 was suggested as a candidate for targeted therapy in cancers expressing high levels of vimentin and E2F1 proteins." (PMID 34452557, 2021). "In both cases, TRIM16 acted to reduce expression of the Hh signaling-activated transcription factor Gli-1, a positive regulator of cancer stem cell self-renewal." (PMID 32226386, 2020). "Previous studies have documented the functions of TRIM16 mainly in cancer, innate immune and other physiological and pathophysiological processes." (PMID 33490087, 2020). "To understand the role of TRIM16 in cancer development, we developed a keratinocyte-specific TRIM16 knockout mouse model." (PMID 31342168, 2019). "The TRIM16‐depletion cripples these machinery leading to the accumulation of toxic misfolded proteins or aggregates intermediates and makes the cancer cell vulnerable to oxidative or proteotoxic stresses in vitro and in vivo." (PMID 30143514, 2018). "The enhanced clearance of oxidative stress-induced misfolded proteins by TRIM16 helps cancer cells to survive in a xenograft tumor mouse model." (PMID 31225461, 2018). "The data obtained from MCF7 cancer cells suggested that all the cell death effects of TRIM16 overexpression required the integrity as well as the functional activation of caspase-2." (PMID 23404198, 2013). "Recently, the multifunctional cellular protein, TRIM16, has been shown to inhibit the growth and proliferation of several different human cancer cell lines." (PMID 23404198, 2013). "TRIM3 and TRIM16 have shown suppressive activity in different cancers." (PMID 36180926, 2022). "Moreover, many studies determined that TRIM16 was an important tumor suppressor in various cancers, including NSCLC, hepatocellular carcinoma, ovarian cancer, and breast cancer, and was related to cell migration, invasion and EMT." (PMID 35230201, 2022). "Therefore, questions have been raised about the exact role of TRIM16, suppressor or activator, in different cancers." (PMID 34452557, 2021). "Notably, several previous reports suggest that Trim16 acts as a tumor suppressor based on its decreased expression in multiple types of cancers and its inhibitory effects on tumor cell proliferation, survival, invasion, and migration." (PMID 33046716, 2020). "Together, these studies indicate a tumor-suppressing function for TRIM16 in human cancers." (PMID 31820796, 2019).
cancer (continued). "We conclude that incapacitating the proteolytic machinery by inhibiting NRF2 and autophagy (or TRIM16) could be a novel therapeutic approach against cancer." (PMID 31225461, 2018). "Together these data suggested that TRIM16 repressed cancer cell replication and migration." (PMID 25333256, 2014). "Thus, further characterisation of the molecular functions of TRIM16 on caspase-2 was conducted mostly in the MCF7 cancer cells." (PMID 23404198, 2013). "Further investigation showed that TRIM16 can reactivate the transcription of RARβ2 by increasing histone H3 acetylation, with the de-acetylation of histone H3 considered to be the most common mechanism of RARβ2 transcriptional repression in retinoid-resistant cancer cells." (PMID 31820796, 2019). "In conclusion, results above have suggested that TRIM16 serves as a tumor suppressor in NB, and defining an effective method to increase TRIM16 protein expression in NB might provide a novel strategy of the cancer therapy." (PMID 31820796, 2019). "Collectively, these results delineate a mechanistic pathway in which LSPs‐mediated mechanical disruption of lysosomes activates Gal3 recruitment and subsequent Trim16/ULK1 engagement, leading to excessive autophagy and cancer cell death." (PMID 41082270, 2026). "•LncPTEN1 facilitates Trim16-mediated Vimentin degradation, thereby suppressing EMT and cancer metastasis." (PMID 40521243, 2025). "While there is limited research on TRIM16 in AML, studies have shown its involvement in other types of cancers and cellular processes." (PMID 40608798, 2025). "Beyond the well-studied genes, our data indicated the potential roles of several other genes, including PAQR5, TRIM16, and ZC3H12A, in modulating cancer cell behavior." (PMID 37958599, 2023). "AKT signaling, known to be active in cancer cells, has been shown to mediate lncRNA VAL binding to Vimentin to eliminate Trim16-dependent Vimentin polyubiquitination and degradation and promote LAD invasion and metastasis." (PMID 36969045, 2023). "Tripartite motif 16 (TRIM16) is a member of the TRIM protein family, which plays an important role in cancers." (PMID 35230201, 2022). "TRIM3 and TRIM16 are two important members of the TRIM family, both of which have shown inhibitory effects in different types of cancer, however a few studies have reported oncogenic activities for them." (PMID 36180926, 2022). "The effect of TRIM16 on epithelial-mesenchymal transition (EMT) and metastasis in cancer cells has a clinical significance in cancer progression." (PMID 34319022, 2021). "The relevance of TRIM-regulated p62 localization to cancer is illustrated by TRIM21 and TRIM16, which act in opposing manners on p62 condensation into cytoplasmic bodies and on activation of the transcription factor Nrf2." (PMID 32226386, 2020). "Our results demonstrate that LSPs induce widespread LMP, which subsequently activates the Galectin‐3 (Gal3)‐Trim16 signaling axis to trigger autophagic cell death in cancer cells—independent of classical apoptotic pathways." (PMID 41082270, 2026). "Most TRIM proteins, such as TRIM44 and TRIM59, exhibit a cancer-promoting role, consistently upregulated across several cancer types, whereas TRIM proteins like TRIM16 suppress cell proliferation and metastasis in neuroblastoma, melanoma, ovarian cancer and breast cancer." (PMID 39451518, 2024). "Furthermore, the up-regulation of the TRIM16 gene leads to the down-regulation of several genes, such as MMP-2, MMP-9, Smo, and Gli-1, which are highly involved in cancer cell invasion." (PMID 36180926, 2022). "TRIM16 is reported to be involved in cellular anti-oxidant mechanisms through Nrf2/ARE signaling, which may play a major role against cancer." (PMID 36180926, 2022). "This may explain the tumor suppressive function of TRIM16 in GC; as reduction in TRIM16 expression leads to the accumulation of mRNAs from β-catenin, Cyclin D, and BCL2 genes and eventually cancer progression." (PMID 34452557, 2021).